MIR656 (microRNA 656)
Synonyms: hsa-mir-656; MIRN656; mir-656
Gene: MicroRNA gene on chromosome 14 (101,066,724 to 101,066,801, forward strand). Ensembl gene ENSG00000207959.
Gene Ontology:
Biological process: miRNA-mediated post-transcriptional gene silencing
Cellular component: RISC complex
Homologues: Orthologues: chimpanzee ptr-mir-656 (100% identical). Paralogues in human: MIR323A (69% identical), MIR323B (64% identical), MIR410 (64% identical), MIR496 (63% identical), MIR154 (62% identical), MIR494 (62% identical), MIR487A (59% identical), MIR539 (56% identical), MIR382 (55% identical), MIR377 (54% identical), MIR409 (54% identical), MIR487B (54% identical), and 4 more.